DMD (dystrophin)
Diseases named in the same sentence as DMD in open-access papers (continued):
Sharing a sentence is not in itself a finding about the gene and the disease.
dystrophinopathy (continued). "Dystrophinopathies are a class of diseases that arise from mutations in the dystrophin gene." (PMID 37362434, 2023). "Furthermore, since female carriers of a pathogenic variant in the DMD gene can develop symptoms of dystrophinopathy ranging from mild muscle weakness to significant disability similar to BMD, NBS would also benefit females." (PMID 37350320, 2023). "Interestingly, a couple of decades ago, young piglets thought to have porcine stress syndrome at slaughterhouses had reduced dystrophin protein and DMD missense mutations, thereby resembling Becker-type dystrophin deficiency." (PMID 36834603, 2023). "Dystrophinopathies are X-linked progressive muscle disorders caused by mutations in the DMD gene." (PMID 36672955, 2023). "However, there is no standard strategy for interpretation of the pathogenicity of DMD duplications during prenatal screening, especially for male fetuses, in which maternally inherited pathogenic DMD variants more frequently cause dystrophinopathies." (PMID 36360209, 2022). "Importantly, the expression of the dystrophin-glycoprotein complex is greatly reduced in dystrophinopathy resulting in the loss of trans-plasmalemmal linkage in dystrophic skeletal muscles." (PMID 36362832, 2022). "Most of the pathogenic DMD variants can be identified by DNA-based standard genetic testing for dystrophinopathies, consisting of multiplex ligation-dependent probe amplification (MLPA) and short-read sequencing of 79 exons and adjacent intronic regions of DMD." (PMID 36092865, 2022). "Dystrophinopathies are due to mutations in the dystrophin (DMD, OMIM *30377) gene." (PMID 33671409, 2021). "DMD is caused by dystrophin deficiency due to mutations in the DMD gene." (PMID 34575126, 2021). "Detailed reviews have been published on the composition of the core dystrophin complex, as well as the role of dystrophin and its associated glycoprotein complex in the multisystemic complications of dystrophinopathy and pathophysiological crosstalk throughout the body." (PMID 33540575, 2021). "Strikingly, according to the gathered reports, only four Latin American countries (Argentina, Brazil, Colombia and Mexico) conduct the screening of DMD small sequence variants, that is to say, the complete molecular diagnostic algorithm for dystrophinopathies (CNV and SNV)." (PMID 34149409, 2021). "The aim of our study was to investigate the relationship between type, size, and location of the mutation that occurs in the DMD gene and their effect on dystrophin protein expression in a cohort of 40 male dystrophinopathy patients and nine females, possible carriers." (PMID 34950096, 2021). "This study shows, to our knowledge, for the first time that several possible poison exons may exist in the DMD gene, which were found to cause dystrophinopathies by promoting poison exon inclusion." (PMID 33050418, 2020). "Dystrophinopathy is diagnosed by identifying the DMD gene mutation, frequently via multiplex ligation-dependent probe amplification (MLPA), which quickly and accurately identifies mutations in ~70% of dystrophinopathy cases that have deletion(s) and/or duplication(s) of the 79 exons in the DMD gene." (PMID 30836656, 2019). "Nonsense mutations in the DMD gene have been reported in 10–15% of dystrophinopathy patients." (PMID 29847600, 2018). "The disintegration of the dystrophin-associated glycoprotein complex renders the plasma membrane of contractile fibres more susceptible to micro-rupturing, which is associated with abnormal calcium handling and impaired cellular signalling in dystrophinopathy." (PMID 35528858, 2018). "DMD gene mutations have been associated with the development of Dystrophinopathies." (PMID 27391342, 2017). "Dystrophinopathies are a group of genetic disorders caused by mutations in dystrophin." (PMID 29367543, 2017). "Such dystrophin positive fibers are frequently observed in animal models of dystrophin deficiency." (PMID 25310701, 2014).
dystrophinopathy (continued). "Hence, future approaches to treating the overall medical complications present in dystrophinopathy have to take into account the remodeling of incapacitating cardiac fibrosis and resulting functional abnormalities in the dystrophin-deficient heart." (PMID 24772416, 2014). "The dystrophinopathies are a group of X-linked muscle diseases caused by mutations in the DMD gene." (PMID 23092449, 2012). "With a clear and specific definition of the transcriptome of dystrophin deficiency, manipulation of identified dysregulated molecules downstream of dystrophin may lead to novel ameliorative approaches for DMD." (PMID 20515474, 2010). "CONCLUSION: High-density SNP-array platforms with low reporting thresholds may incidentally detect a subset of exon-level copy number variations involving the DMD gene during routine prenatal testing and thereby contribute to early recognition of potential dystrophinopathy-related variants." (PMID 41792804, 2026). "However, to date, at least 20 unique DMD variants have been identified across 15 different dog breeds, including point mutations and various chromosomal rearrangements, illustrating the genetic heterogeneity of dystrophinopathies." (PMID 41300820, 2025). "Therefore, atypical splicing variants in sarcoglycan genes that can be easily missed by routine genetic testing should be excluded before establishing a genetic diagnosis of dystrophinopathy in patients with uncertain DMD missense variants and overlapping features with sarcoglycanopathies." (PMID 38486238, 2024). "Furthermore, the reduced expression of dystrophin in the sarcolemma could be confirmed by immunohistochemistry, which let us hypothesize that observed abnormalities may have been caused by a dystrophinopathy." (PMID 34465383, 2021). "Contrary to lower percentages of PAX7- and MYOD1-positive nuclei in DMD-R3381X cultures, these results suggest that dystrophin deficiency may have an effect on translation of PAX7 and MYOD1 or as yet unidentified mechanisms, although this will require further investigation." (PMID 34516770, 2021). "In cases where the DMD variant is pathogenic and clinical assessment supports a diagnosis of dystrophinopathy, this may explain the patient’s symptoms if they are known to be associated with dystrophinopathy." (PMID 32424326, 2020). "In addition to dystrophinopathies, many muscle diseases are caused by genetic abnormalities in proteins which form complexes with dystrophin (e.g., dystrophin–glycoprotein complexes), and it has been reported that abnormalities in the same responsible genes as those of MD also cause DCM." (PMID 31394715, 2019). "In order to further explore the functionality of the dystrophin isoform, missing the domain encoded by exon 5, we used an AO designed to exclude exon 5 from the mature Dmd transcript in wild-type mice, essentially creating a transient dystrophinopathy mouse model." (PMID 26745801, 2016). "Similarly, a concomitant reduction in dystrophin and any of the SGCs may illustrate the importance of considering coexisting dystrophinopathies in patients with sarcoglycan-deficient LGMD." (PMID 25050186, 2014). "The analysis of both types of mutations, the study of their positions along the DMD gene and their effects on the transcript processing and protein levels helps to define the correlations with clinical presentation and to build a clear understanding of the molecular pathology of dystrophinopathies." (PMID 21396098, 2011). "This phenotype models the situation in female dystrophinopathy and dystrophic muscle in which dystrophin has been incompletely restored by partially effective experimental therapeutics." (PMID 41944729, 2026). "Of the 10 patients with dystrophinopathies (median age, 5.95 years), seven were DMD, and three were BMD." (PMID 41582627, 2026).
dystrophinopathy (continued). "Although this bias cannot be ruled out, we compared the results with those of 35 patients with dystrophinopathy (26 with DMD, 6 with BMD, and 3 carriers), who showed BNP levels > 100 pg/mL at the NHO Osaka Toneyama Medical Center in 2019." (PMID 39789553, 2025). "In this study, we evaluated the diagnostic yield of an integrated approach combining long-read sequencing of the entire DMD gene with RNA-seq in a cohort of 50 dystrophinopathy patients who had remained undiagnosed following standard MLPA and ES." (PMID 41321997, 2025). "In order to shed light on the mechanisms responsible for the clinical manifestations of dystrophinopathy in females, we recruited a cohort of 47 DMD heterozygous females, 27 asymptomatic and 20 symptomatic." (PMID 40035839, 2025). "Dystrophinopathies are genetic disorders linked to pathogenic variants in the DMD gene, which encodes the dystrophin protein." (PMID 39451985, 2024). "The utilization of MLPA is presently regarded as a labor-efficient primary method for detecting deletions and duplications of single or multiple exons in the DMD gene, as approximately 70% of dystrophinopathy patients exhibit such genetic alterations." (PMID 38195599, 2024). "Even the fear of possible cardiac rejection is limited—at least for patients with dystrophinopathies—because the missing/poor dystrophin present makes the production of antibodies against the deleted region of dystrophin gene very unlikely." (PMID 38791328, 2024). "Pathogenic amino acid substitutions in terms of missense variants count for up to <1% of dystrophinopathies and can lead to either DMD or BMD based on their pathogenic impact of the DMD protein structure and stability." (PMID 39767645, 2024). "The postulated mechanism for DMD carriers to become patients with dystrophinopathy is attributed to the extent of random X-inactivation of the normal X chromosome versus the dystrophic X chromosome." (PMID 39075955, 2024). "To date, 28 balanced translocations disrupting the DMD gene have been reported in female dystrophinopathy patients." (PMID 39063034, 2024). "The porcine model of dystrophinopathy (DMD pig) is characterized by a deletion in exon-52 of the DMD gene and exhibits progressive cardiomyopathy." (PMID 37509144, 2023). "These diseases share a common pathomechanism where, due to the loss of the anchoring dystrophin (DMD, dystrophinopathy) or due to mutations in sarcoglycan-encoding genes (LGMDR3 to LGMDR6), the α-sarcoglycan ecto-ATPase activity is lost." (PMID 37298386, 2023). "Any mutation in the DMD gene leads to dysfunction of the dystrophin protein and consequently all dystrophin-associated glycoproteinsm, which furthermore causes muscular degeneration such as DMD and the more benign Becker type of dystrophinopathy." (PMID 36834757, 2023). "As the incidence of dystrophinopathies is significantly higher than that of LGMDs, we decided to investigate first for deletions/duplications in the DMD gene." (PMID 37298193, 2023). "Given that DMD is the largest human gene, it is unsurprising that some cases of transposon-induced dystrophinopathies have been described." (PMID 37298193, 2023). "Animal studies and clinical studies have shown that even low levels of dystrophin can improve functional outcomes in DMD and are associated with milder dystrophinopathy." (PMID 34788571, 2022). "ASD genotype–phenotype studies with dystrophinopathies, although scarce, suggest the relevance of both longest and shorter dystrophin isoforms, differently to what has been observed for ID only." (PMID 37861890, 2022). "We therefore present a review of the literature focused on the ASD prevalence among dystrophinopathies, the relevance of the dystrophin isoforms, and most particularly the relevance of the genetic background to the etiology of ASD in these patients." (PMID 37861890, 2022).
dystrophinopathy (continued). "Our results show that the clinical characteristics of a dystrophin mutant dog are similar to pathologic features in human dystrophinopathy." (PMID 35270040, 2022). "With this in mind, we observed the clinical manifestations of dystrophinopathy in the dystrophin mutant dog with increased CK using MRI." (PMID 35270040, 2022). "To establish the dystrophin mutant dog as a valid dystrophinopathy model, we performed ECG analysis in an age-matched control and the dystrophin mutant dog." (PMID 35270040, 2022). "For example, molecular confirmation of dystrophinopathy determines applicability of corticosteroid therapy, as DMD is one of the MDs showing fruitful results from this treatment." (PMID 34149409, 2021). "Accordingly, muscle biopsy showed primitive muscle damage, and immunofluorescence analysis revealed a significant reduction in dystrophin, compatible with dystrophinopathy, which was confirmed by molecular analysis." (PMID 34675869, 2021). "Moreover, it is alarming the reduced number of countries providing the DMD full mutational analysis to the affected individuals, which, as it was highlighted throughout the manuscript, is now considered the foundations of the theragnosis for dystrophinopathies." (PMID 34149409, 2021). "The pattern of dystrophin expression and functionality in dystrophinopathy patients is variable due to multiple factors, such as molecular functionality of the dystrophin and its distribution." (PMID 34498054, 2021). "In other works, homology-directed repair was used to restore low-level dystrophin expression in mdx and other murine dystrophinopathy models." (PMID 34445659, 2021). "Hence, the difference between severe versus more benign forms of dystrophinopathy is based on the type of genetic alterations and whether particular mutations cause the loss of dystrophin or the production of an abnormal but still semi-functional protein product." (PMID 34553265, 2021). "There is currently no cure for the dystrophinopathies but in the last 10 years several therapeutic approaches aimed at inducing the production of dystrophin protein have been investigated." (PMID 34498054, 2021). "Dystrophin expression represents an important biomarker for evaluating the efficacy of stem cell transplantation in dystrophinopathy." (PMID 33413615, 2021). "Intriguingly, miR-146b is also known to down-regulate dystrophin in multiple muscle diseases, is increased in dystrophinopathies and in myositis, and is also drug-responsive in the mdx mouse model of DMD." (PMID 33228131, 2020). "Among 1497 dystrophinopathy patients in our cohort, we found 18 cases with positive dystrophin staining from 363 cases with a nonsense or frameshift mutation in DMD gene." (PMID 31919629, 2020). "BMD presents with partially functioning dystrophin, and is therefore a milder yet more variable form of dystrophinopathy, with about 50% of adults with BMD maintaining the ability to walk." (PMID 32469921, 2020). "Conversely, mutations that respect the ORF lead to the expression of qualitatively and/or quantitatively altered dystrophin, result in the milder allelic form of dystrophinopathy, Becker muscular dystrophy (BMD, MIM #300376)." (PMID 31083420, 2019). "These lncRNAs have a repressive role on the full-length dystrophin isoform and their expression is inversely correlated with dystrophin long isoform in the muscle of female dystrophinopathy carriers." (PMID 31681761, 2019). "BMD involves partially functioning dystrophin, and is therefore a milder yet more variable form of dystrophinopathy, with an incidence of 2 in 100,000 male births." (PMID 30544630, 2018). "Because Nav1.5 interacts with dystrophin and other protein members of the DAPC, the syntrophins, it is conceivable that the disturbance of these interactions, in the case of dystrophin deficiency, impairs Nav1.5 expression and localization." (PMID 30360568, 2018).
dystrophinopathy (continued). "This links DMD, currently considered to be responsible only for the development of the monogenic orphan dystrophinopathies, to one of the most frequent diseases such as cancer." (PMID 27391342, 2017). "This study retrospectively evaluated the results of gene analysis for 1497 patients with dystrophinopathies with clinical features and dystrophin immunostaining." (PMID 28859693, 2017). "In general, the phenotypic spectrum observed in the dystrophinopathies is related to the specific tissue and degree of dystrophin expression, which, in large part, is determined by the “reading frame rule”." (PMID 29367543, 2017). "A synonym nucleotide substitution (c.4299G > T, p.Gly1433Gly), likely disrupting an ESE in exon 3127, caused mild dystrophinopathy (NSAA 34/34) in two brothers aged 35 and 47, with 10~30% dystrophin with slightly reduced molecular weight at immunoblot." (PMID 27582364, 2016). "The introduction of a simple pre-fractionation step enabled the simultaneous proteomic comparison of the reduction in the dystrophin-glycoprotein complex and secondary changes in the mdx-4cv mouse model of dystrophinopathy in a single analytical run." (PMID 26067837, 2015). "Dystrophin was found to be the most significantly reduced protein species in the mdx-4cv animal model of dystrophinopathy." (PMID 28248273, 2015). "In this paper we describe 576 dystrophinopathy families and discuss the mutational spectrum associated with the DMD gene and its impact on the dystrophin structure." (PMID 26284620, 2015). "The dermal fibroblasts were derived from a skin biopsy taken from a dystrophinopathy patient in Ireland with a deletion of DMD exons 45–47." (PMID 26247048, 2015). "This highlights the enormous loss of working capacity and productivity due to informal care required for dystrophinopathies, and in particular for DMD." (PMID 25519771, 2014). "Herein we report our results concerning the clinical phenotype, dystrophin expression and DMD molecular analysis in 105 dystrophinopathy patients, presenting 98 different point mutations." (PMID 23536893, 2013). "As a result, more dystrophinopathy patients have become aware of the necessity of confirming their diagnosis via analysis of the DMD gene." (PMID 23601510, 2013). "This study has great implications, not only in the elucidation of the physiological role of dystrophin in cells, but also in the investigation of dystrophinopathies and their pathogenesis." (PMID 23028937, 2012). "Due to the recent advances in drug, molecular and cell therapies dystrophinopathies are a field of intense interest in terms of both phenotype stratification and dystrophin gene regulation." (PMID 23028937, 2012). "Despite their relevance for the biology of the dystrophin gene, our data become particularly significant for a more comprehensive understanding of dystrophinopathies and eventually for the better design of the therapeutic approaches." (PMID 23028937, 2012). "Together, these discoveries broaden the genetic landscape of DMD mutations and highlight the importance of non-canonical splicing mechanisms in dystrophinopathy pathogenesis." (PMID 41321997, 2025). "The most prevalent MDs are dystrophinopathies, characterized by a wide spectrum of loss-of-function mutations in the DMD gene that causes reduced to no synthesis of dystrophin, a protein crucial for the integrity of the sarcolemma." (PMID 39859495, 2025). "Dystrophinopathies are a group of neuromuscular disorders caused by variants in the dystrophin-encoding gene, leading to absent or deficient dystrophin production and progressive muscle degeneration." (PMID 40218127, 2025). "Despite the expanding catalog of known DMD variants in dogs, dystrophinopathy has not been documented in the Shiba Inu breed." (PMID 41300820, 2025).